NLRP1 (NLR family pyrin domain containing 1)
Diseases named in the same sentence as NLRP1 in open-access papers (continued):
Sharing a sentence is not in itself a finding about the gene and the disease.
lung adenocarcinoma (13 papers, 2021 to 2025). A carcinoma that arises from the lung and is characterized by the presence of malignant glandular epithelial cells. "CASP1, NLRP3, AIM2, and NLRP1 are core pyroptotic genes in lung adenocarcinoma, significantly associated with immune cell infiltration, diagnosis, and prognosis in this condition." (PMID 40026444, 2025). "The results showed that CASP1, NLRP3, AIM2, and NLRP1 exhibited excellent diagnostic efficacy, suggesting their potential utility as diagnostic biomarkers for lung adenocarcinoma." (PMID 40026444, 2025). "Evaluation using ROC curves for core genes indicated that CASP1, NLRP3, AIM2, and NLRP1 demonstrate excellent diagnostic potential for lung adenocarcinoma and may serve as diagnostic markers for the disease." (PMID 40026444, 2025). "This further confirms the pyroptosis core gene CASP1, NLRP3, AIM2, and NLRP1 expression levels in lung adenocarcinoma and their connection to immune infiltration." (PMID 40026444, 2025). "Several studies have explored the potential of NLRP1 as a prognostic biomarker in various cancers, including lung adenocarcinoma, gastric cancer, prostate cancer, pancreatic cancer, head and neck squamous cell carcinoma, and laryngeal carcinoma." (PMID 40237399, 2025). "Several additional multi‐omics analyses exploring pyroptosis‐related genes in lung adenocarcinoma consistently showed downregulation of NLRP1 in LUAD tissues compared to normal tissues." (PMID 40237399, 2025). "Our results indicated a significant elevation in NLRP1 protein expression in normal samples relative to primary tumors in lung adenocarcinoma patients." (PMID 40237399, 2025). "Our focus was constructing a diagnostic and prognostic model for lung adenocarcinoma based on the core genes—CASP1, NLRP3, AIM2, and NLRP1." (PMID 40026444, 2025). "We further analyzed the influence of core genes on lung adenocarcinoma prognosis, and survival analysis revealed a significant association between CASP1, NLRP3, NLRP1, and AIM2 and overall survival in patients with lung adenocarcinoma." (PMID 40026444, 2025). "NLRP1 exhibited differential expression patterns across various cancers, with elevated expression correlating with a more favourable prognosis in lung adenocarcinoma (LUAD) and pancreatic adenocarcinoma (PAAD)." (PMID 39318060, 2024). "The expression of NLRP1 was positively correlated with the degree of tumor-infiltrating immune cells in lung adenocarcinoma." (PMID 35432539, 2022). "It has also been reported that the regulation of TME by NLRP1 affects the prognosis of patients with lung adenocarcinoma." (PMID 36246601, 2022). "NLRP1, the first identified inflammasome-forming sensor, is thought to be involved in cancer, yet its definite function in lung adenocarcinoma (LUAD) remains unclear." (PMID 39258674, 2024). "Furthermore, it has been discovered that NLRP1 downregulation promotes tumorigenesis, including lung adenocarcinoma and colorectal cancer." (PMID 36118860, 2022). "Low expression of NLRP1 was correlated with poor overall survival in lung adenocarcinoma." (PMID 35432539, 2022). "However, NLRP1 has not been reported to be linked to LUAD (lung adenocarcinoma) risk, prognosis, immunotherapy or any other treatments." (PMID 33658393, 2021). "not only constructed a pyroptosis-related prognostic predication model involving 5 PRGs (CASP6, NLRP7, NOD1, NLRP1, and NLRP2) in lung adenocarcinoma, but also established a network of mRNA–miRNA–lncRNA closely relating to PRGs." (PMID 35912258, 2022). "Another comprehensive bioinformatics analysis also performed on lung adenocarcinoma identified a prognostic pyroptosis-related gene signature containing five genes (NLRP7, NLRP1, NLRP2, NOD1, and CASP6)." (PMID 36324154, 2022).
Autoimmunity (12 papers, 2011 to 2026). The occurrence of an immune reaction against the organism's own cells or tissues. "The NLRP1 gene is implicated in rheumatoid arthritis, Celiac disease, Addison’s disease, and type 1 diabetes, linking it to inflammation, autoimmune disorders, and caspase-mediated apoptosis." (PMID 40951041, 2025). "Case 2 demonstrates a clustering of autoimmune conditions consistent with probable APS-2, supported by the presence of an NLRP1 variant and a family history of autoimmunity." (PMID 40951041, 2025). "But of all NLRs discussed, NLRP1 is the most widely implicated in susceptibility to autoimmunity in human studies." (PMID 24409181, 2013). "Defects in NLRP1 have been linked to a variety of autoimmune disorders." (PMID 24137163, 2013). "The activation of the inflammasome has been proposed as a mechanism of autoimmunity in MS patients, a hypothesis that is supported by rare variants in inflammasome components NLRP1, NLRP3, NLRP5 and NLRP9 which were identified in MS families, or found to correlate with disease course and severity." (PMID 31170158, 2019). "To date, the role of inflammasomes in autoimmunity have largely focused on NLRP3 and AIM2, but other inflammasome molecules such as NLRP1, and NLR family CARD domain-containing protein 4 (NLRC4) have also been implicated in autoimmunity." (PMID 37081890, 2023). "Additionally, inflammasomes play a vital role in the development and progression of autoimmunity, inflammation and metabolic disease, and many SNPs in inflammasome-associated genes, including NLRP1, NLRP3, NLRP12 and CARD8, are involved in and associated with patient susceptibility to T1DM." (PMID 34867336, 2021). "It is plausible that deregulation of an NLRP1 inflammasome effector function is at the basis of the autoimmunity phenotypes." (PMID 24137163, 2013). "Until a mechanistic understanding of these SNPs is discovered, the association with autoimmunity does not provide a paradigm in which to develop a role for NLRP1 in the initiation of adaptive immune processes directed against self molecules." (PMID 24409181, 2013).
colorectal cancer (12 papers, 2015 to 2024). A primary or metastatic malignant neoplasm that affects the colon or rectum. "The expression level of NLRP1 in colorectal cancer tissues is significantly lower than that in adjacent normal tissues, and NLRP1 can inhibit tumorigenesis of colorectal cancer." (PMID 36186792, 2022). "Studies have shown that the mRNA and protein levels of NLRP1 are reduced in colorectal cancer cells compared to normal cells and the anticancer drug DAC increases the expression of NLRP1 to inhibit the progression of colorectal cancer." (PMID 35669428, 2022). "The expression of NLRP1 in colorectal cancer was decreased compared with normal tissues, and a higher tumor incidence was observed in NLRP1−/− mice." (PMID 34805183, 2021). "Compared to healthy intestinal epithelial tissue, NLRP1 has been found to be down-regulated in colorectal cancer." (PMID 33658393, 2021). "During the early stage of colorectal cancer, elevated IL-18 secretion facilitated by NLRP1/NLRP3/pyrin could protect against colorectal cancer through the promotion of epithelial barrier regeneration during the early stages of colorectal cancer." (PMID 35990696, 2022). "Moreover, the NLRP1 expression level reduced with the raising of colorectal cancer progression and the lowest level measured in stage III/IV patients." (PMID 33658393, 2021). "Case reports have shown significantly decreased the expression levels of NLRP1, NLRP3, NLRC4, AIM2, and other inflammasomes in patients with colorectal cancer compared to healthy controls." (PMID 38756775, 2024). "They found that the mRNA expression of NLRC3 as an inflammation checkpoint; NLRP1, NLRP3 and NLRC4 as the components of inflammasome and AIM2 were all decreased in colorectal cancer." (PMID 34571825, 2021).
congenital toxoplasmosis (12 papers, 2012 to 2024). Toxoplasma infection that is present from birth. "NLRP1-associated susceptibility alleles are directly associated with human congenital toxoplasmosis." (PMID 36755348, 2023). "In humans, congenital toxoplasmosis has been linked to NLRP1 polymorphisms and NLRP1 knockdown experiments found an association with premature host cell death following T. gondii infection." (PMID 35646724, 2022). "The human NLRP1 gene is highly polymorphic and GWAS studies have linked NLRP1 SNPs to congenital toxoplasmosis, Addison’s disease (hypocortisolism and adrenal insufficiency) but also to generalized vitiligo." (PMID 33925158, 2021). "The clinical relevance of NLRP1 inflammasomes against Toxoplasma gondii is also evident in individuals with specific single-nucleotide polymorphisms in the NLRP1 gene, which are linked to congenital toxoplasmosis." (PMID 31118894, 2019). "Further studies showed that single nucleotide polymorphisms (SNPs) of human NLRP-1 are associated with susceptibility to congenital Toxoplasmosis." (PMID 28484433, 2017). "Human susceptibility to congenital toxoplasmosis has also been proved to link to SNPs of NLRP-1; however, the mechanism by which T. gondii activates NLRP3/1-infammasomes is poorly understood." (PMID 28484433, 2017). "Moreover, NLRP1 plays a role in human monocyte control of Toxoplasma, and polymorphisms in NLRP1 also influence the severity of congenital toxoplasmosis." (PMID 38376248, 2024). "The inflammasome forming NLR NLRP1 (nucleotide binding domain and leucine rich repeat containing receptor P1) has previously been identified as an essential sensor of T. gondii in rodents and mutations in NLRP1 have been shown to confer susceptibility for human congenital toxoplasmosis." (PMID 27378827, 2016). "SNPs prevalent in this N-terminal region of human NLRP1 have been correlated with the severity of human congenital toxoplasmosis." (PMID 24626226, 2014).
type 1 diabetes (12 papers, 2013 to 2025). "Single-nucleotide polymorphisms in NLRP1 are associated with an increased risk of developing type-1 diabetes and systemic lupus erythematosus (SLE) in Brazilian population cohorts." (PMID 33584697, 2020). "Polymorphisms in NLRP1 affect susceptibility to type 1 diabetes in the Chinese Han population." (PMID 36967805, 2023). "Genomic studies of NLRP1 have identified mutations associated with autoinflammatory diseases in humans, including systemic sclerosis, Crohn’s disease, Addison’s disease, rheumatoid arthritis, type-1 diabetes, and vitiligo." (PMID 33584697, 2020). "The aim of this study was to clarify the association of two single-nucleotide polymorphisms (SNPs) (rs11651270 and rs2670660) in the NLRP1 (NLR family pyrin domain containing 1) gene with type 1 diabetes (T1D) in the Chinese Han population." (PMID 31396539, 2019). "In addition, NLRP1 has a protective effect in type 1 diabetes." (PMID 36993972, 2023). "Studies have shown that NLRP1 and NLRP3 inflammasomes exert a synergistic effect and have a protective function on the body in the early stage of type 1 diabetes." (PMID 36993972, 2023).
colon cancer (11 papers, 2015 to 2025). "In colon cancer, compared to wild type mice, the loss of NLRP1 can cause the increasing of tumorigenesis driven by inflammation, which has been proved in the Nlrp1b-/- mouse models." (PMID 33658393, 2021). "NLRP1 expression levels were downregulated in biopsied tissues of colon cancer patients compared with healthy controls, suggesting that NLRP1 can act as a key regulator of colon homeostasis." (PMID 37497237, 2023). "In this study, we analyzed mononucleotide repeats in coding sequences of NLRP1, NLRP2, NLRP4 and NLRP9, and found 1, 1, 1 and 8 frameshift mutation (s) in gastric (GC) and colonic cancers (CRC), respectively." (PMID 34257569, 2021). "High NLRP1 expression has been shown to inhibit colon cancer cell growth." (PMID 38166691, 2024). "To test whether ER stress specifically induces NLRP1 gene expression, we stimulated HCT116 human colon cancer cells with various inflammatory stimuli and measured mRNA expression of both NLRP1 and NOD1 (NLRC1), which is another human NLR family member." (PMID 26086088, 2015).
metabolic syndrome (10 papers, 2016 to 2025). A cluster of metabolic risk factors for CARDIOVASCULAR DISEASES and TYPE 2 DIABETES MELLITUS. "Dysregulation of NLRP1 signaling has been implicated in the pathogenesis of numerous diseases, including autoimmune disorders, metabolic syndromes, and neurodegenerative conditions." (PMID 40242759, 2025). "One wonders whether single nucleotide variant of the human NLRP1 gene correlates with IL-18 levels and consequently with the susceptibility of obese individuals to develop dyslipidemias and/or T2D." (PMID 31554824, 2019). "However, a consensus on precisely how the inflammasome sensor proteins implicated in the metabolic syndrome and diabetic conditions, NLRP1 and NLRP3, come to be activated in these states, has yet to be reached." (PMID 29515457, 2018).
systemic lupus erythematosus (10 papers, 2013 to 2024). An autoimmune multi-organ disease typically associated with vasculopathy and autoantibody production. "It has been reported that NLRP1 mutations can play a role in inflammatory diseases such as psoriasis, rheumatoid arthritis (RA) or in systemic lupus erythematosus (SLE)." (PMID 35457026, 2022). "Mutations in the Nlrp1 gene have been linked to susceptibility to vitiligo-associated autoimmune diseases, systemic lupus erythematosus (SLE) and RA." (PMID 28588486, 2017). "Patients with systemic lupus erythematosus (SLE) suffer from disordered Th1/Th2 and Treg/Th17 balances, evidence has demonstrated that NLRP3, NLRP1, NLRC4, and AIM2 were involved in the regulation of Th1, Tfh, and Th17 cell-mediated immune responses." (PMID 38177104, 2024).
atherosclerosis (9 papers, 2020 to 2026). A disease characterized by the build-up of fatty material and calcium deposition in the arterial wall resulting in partial or complete occlusion of the arterial lumen. "Further, NLRP1 stimulates the progression of cardiovascular disease, more specifically atherosclerosis and was also linked to peripheral artery disease." (PMID 34169069, 2021). "NLRP1 inflammasomes are involved in a variety of diseases, especially cardiovascular diseases, and NLRP1 expression has been closely associated with various diseases, such as atherosclerosis and myocardial ischemia/reperfusion (I/R) injury." (PMID 37492291, 2023). "Research has shown that NLRP1, a well-known inflammasome, contributes to the progression of atherosclerosis, myocardial infarction, and heart failure." (PMID 40124544, 2025). "NLRP1 inflammasome activation promotes MI/RI18 and NLRP1 is upregulated in atherosclerosis." (PMID 35699193, 2022). "So far, it has also reported that in atherosclerosis, triglycerides and VLDL-cholesterol contribute to the activation of NLRP1 through NF-κB motivation in endothelial cells." (PMID 32922182, 2020). "All other inflammasomes remain poorly understood in atherosclerosis, except AIM2, NLRP1, and NLRC4." (PMID 40564905, 2025). "NLRP1 gene expression was found to be significantly higher in the patients with aortic occlusive disease (AOD) and coronary stenosis suggesting its importance in the development of atherosclerosis." (PMID 33584697, 2020).
rheumatoid arthritis (9 papers, 2013 to 2025). A chronic, systemic autoimmune disorder characterized by inflammation in the synovial membranes and articular surfaces. "Polymorphisms in NLRP1 to be associated with increased susceptibility to rheumatoid arthritis (RA), multiple sclerosis (MS), and systemic lupus erythematous (SLE)." (PMID 33036374, 2020). "Polymorphisms in the NLRP1 gene are linked to Crohn’s disease, rheumatoid arthritis (RA) and systemic sclerosis." (PMID 31118894, 2019). "Single nucleotide polymorphisms (SNPs) in the NLRP1 have been implicated in several complex autoimmune conditions such as juvenile idiopathic arthritis, rheumatoid arthritis (RA), vitiligo, autoimmune Addison's disease, and Type I Diabetes." (PMID 29850521, 2018). "However, in generalized vitiligo high-risk NLRP1 haplotypes display elevated IL-1β processing, and in rheumatoid arthritis patients, NLRP1 transcripts are elevated." (PMID 24367371, 2013).
depression (8 papers, 2020 to 2025). "Our results have displayed that NLRP1 inflammasome-driven inflammatory response is implicated in depression." (PMID 32513185, 2020). "In this study, we established depression models of mice via four different chronic stress stimuli, which are major risk factors of MDD, and investigated the role of NLRP1 inflammasome in depression." (PMID 32513185, 2020). "Autophagy dysfunction contributes to NLRP1 inflammasome-linked depressive-like behavior in mice and the regulation of autophagy could be a valuable therapeutic strategy for the management of depression." (PMID 38178196, 2024). "For instance, Hyperoside significantly mitigates depression-like behaviors in chronic stress-induced mice by inhibiting the NLRP1 inflammasome and modulating the CXCL1/CXCR2/BDNF signaling pathway, leading to improved anhedonia and reduced immobility time." (PMID 40444002, 2025). "Both nucleotide-binding oligomerization domain, leucine-rich repeat and pyrin domain-containing 1 (NLRP1) inflammasome and autophagy have been reported to implicate in the pathological processes of depression." (PMID 38178196, 2024). "To research the influence of Hyp on the depression-like behavior of mice mediated by the NLRP1 inflammasome, we detected the mRNA levels of CXCL1, CXCR2, and BDNF in the hippocampus of mice." (PMID 36556951, 2022). "However, it is unclear whether NLRP1 inflammasome is implicated in the development of depression." (PMID 32513185, 2020). "In the present study, we demonstrated that NLRP1 inflammasome and related inflammatory signaling are activated in chronic stress-induced animal model of depression." (PMID 32513185, 2020). "These indicate that stress stimuli lead to the assembly of NLRP1 inflammasome and consequently triggers inflammatory response, which probably contributes to the development of depression." (PMID 32513185, 2020). "To investigate the role of NLRP1 inflammasome in depression, we first established animal models by four chronic stimuli including CUMS, CRS, RSDS, and CSDS." (PMID 32513185, 2020). "The present study demonstrated that NLRP1 inflammasome-driven inflammatory process is a critical player in chronic stress-induced depression-like behaviors." (PMID 32513185, 2020). "NLRP1 inflammasome and autophagy have been reported to implicate in the development of depression." (PMID 38178196, 2024). "However, the mechanistic interplay between NLRP1 inflammasome, autophagy, and depression is still poorly known." (PMID 38178196, 2024). "However, further studies will be made to clarify the precise mechanism of the interplay of NLRP1 inflammasome and autophagy in depression." (PMID 38178196, 2024). "Consequently, we investigated the interplay of NLRP1 inflammasome and autophagy in an animal model of depression induced by chronic social defeat stress (CSDS)." (PMID 38178196, 2024). "However, the precise mechanism of how NLRP1 inflammasome participates in the development of depression needs to be further clarified." (PMID 38178196, 2024). "The mice with knocked down NLRP1 inflammasome activity displayed diminished chronic stress-induced depressive-like demeanor, indicating that inflammasome-mediated IL-18-induced CNS inflammation can indeed lead to depression." (PMID 36614020, 2022). "This research showed that Hyp is the main antidepressant component of HP, and its antidepressant effect may be through the NLRP1 signaling pathway to improve depression-like behavior in mice." (PMID 36556951, 2022). "Therefore, NLRP1 inflammasome is a potential antidepressant target and inhibition of NLRP1 inflammasome can protect against chronic stress-induced depression-like behaviors." (PMID 32513185, 2020). "However, the mechanistic interplay between NLRP1 inflammasome, autophagy, and depression is still largely unknown." (PMID 38178196, 2024).